SIGLEC8 (sialic acid binding Ig like lectin 8)
Description:
Putative adhesion molecule that mediates sialic-acid dependent binding to blood cells. Preferentially binds to alpha-2,3-linked sialic acid. Also binds to alpha-2,6-linked sialic acid. The sialic acid recognition site may be masked by cis interactions with sialic acids on the same cell surface. Recognizes simultaneously epitopes having a terminal N-acetylneuraminic acid (sialic acid) and an underlying 6-O-sulfated galactose. Preferentially binds to Gal-6-sulfated sialyl-Lewis X glycan epitopes.
Synonyms: Siglec-8; SAF2; SIGLEC8L; MGC59785
Tractability: Small molecule: a structure with a bound ligand is known. Antibody: a drug acting on it is in phase 2 or 3 trials; UniProt predicts a signal peptide or a membrane-spanning region; its Gene Ontology location is reachable by antibodies, with medium confidence.
Gene: Protein-coding gene on chromosome 19 (51,450,847 to 51,458,469, reverse strand). Ensembl gene ENSG00000105366.
Subcellular location: Membrane
Subcellular location (Human Protein Atlas): Cytosol
Pathways (Reactome):
Immune System: Immunoregulatory interactions between a Lymphoid and a non-Lymphoid cell
Gene Ontology:
Molecular function: protein binding; carbohydrate binding; sialic acid binding; transmembrane signaling receptor activity
Biological process: cell adhesion; signal transduction
Cellular component: membrane; plasma membrane
Genetic constraint (gnomAD): Loss-of-function variants: 31 observed, 42.77 expected, observed/expected ratio (o/e) 0.72, 90% interval 0.54 to 0.98. The upper end of that interval is the gene's LOEUF score, 0.98, which puts it in group 4 of 6, group 1 being the genes least tolerant of losing a copy. Missense variants: 610 observed, 620.95 expected, observed/expected ratio (o/e) 0.98, 90% interval 0.92 to 1.05. Synonymous variants: 262 observed, 270.78 expected, observed/expected ratio (o/e) 0.97, 90% interval 0.87 to 1.07.
Homologues: Orthologues: chimpanzee SIGLEC8 (97% identical), mouse Siglece (52% identical), rat Siglec8 (50% identical), tropical clawed frog siglecl2 (26% identical), tropical clawed frog siglecl2 (25% identical), tropical clawed frog siglecl1 (23% identical), tropical clawed frog siglecl1 (17% identical). Paralogues in human: SIGLEC12 (68% identical), SIGLEC7 (68% identical), SIGLEC9 (66% identical), SIGLEC6 (46% identical), SIGLEC5 (46% identical), SIGLEC10 (41% identical), SIGLEC11 (41% identical), CD33 (40% identical), SIGLEC14 (39% identical), SIGLEC1 (24% identical), MAG (21% identical), SIGLEC16 (19% identical), and 4 more.
Diseases named in the same sentence as SIGLEC8 in open-access papers:
SIGLEC8 is named in the same sentence as 16 diseases in open-access papers, as found by Europe PMC text mining. Sharing a sentence is not in itself a finding about the gene and the disease. The quoted sentences say what the papers report.
asthma (10 papers, 2018 to 2026). "Genetic studies of Siglec‐8 have identified several variants associated with higher risk for asthma (rs36498, rs10409962, and rs11672925), but these mutations have not yet been linked to microglial function." (PMID 33289969, 2020). "Previous work on Siglec‐F and Siglec‐8 has shown that antibody engagement of these receptors causes a pro‐apoptotic response in eosinophils, making them a potential drug target for asthma." (PMID 33289969, 2020). "Asthma is an eosinophil, expressing Siglec-8, mediated disease and it has been shown that polymorphisms in the SIGLEC8 gene are linked to the development of asthma." (PMID 30581432, 2018). "Clinically, SIGLEC8 may play a role in preventing chronic lung inflammation in asthma by inducing cell death of activated eosinophils, supported by the observation that polymorphisms have been associated with asthma susceptibility in humans." (PMID 30619265, 2018). "SIGLEC8 is highly expressed on eosinophils and mast cells in the airways of patients with asthma, particularly in T2-high disease." (PMID 41601686, 2026). "Moreover Siglec8+ (human homolog to murine SiglecF) were increased in patients with Asthma-COPD overlap." (PMID 36776857, 2023). "Asthma and AR share eight common genes (CLC, EMR4P, IL5RA, FRRS1, HRH4, SLC29A1, SIGLEC8, IL1RL1) that are presumed to describe the link for multimorbidity." (PMID 36825519, 2023). "In accordance, we found the eosinophil marker genes RNASE2 (ribonuclease A family member 2), RNASE3, SIGLEC8 (sialic acid binding Ig-like lectin 8) and IL5RA as well as PRSS33 (serine protease 33) being exclusively expressed in eosinophils in the deconvolved asthma data." (PMID 33076907, 2020).
diabetic nephropathy (1 paper, 2022). "Moreover, SIGLEC8, the human counterpart of Siglec-F, was upregulated in renal tissues from patients with diabetic nephropathy or FSGS compared with healthy controls as well as in fibrotic renal tumor tissues from patients compared with their healthy renal tissues." (PMID 35482420, 2022). "Compared to healthy renal tissues, the renal tissues of patients with diabetic nephropathy and FSGS exhibited significantly increased expression of both FCGRIIIB (a surrogate marker of neutrophils) and SIGLEC8." (PMID 35482420, 2022).
duodenitis (1 paper, 2023). Acute or chronic inflammation of the duodenum. "The results of a phase 2 trial using lirentelimab (a monoclonal antibody targeting the eosinophil and mast cell transmembrane protein Siglec8) demonstrated a slightly dysphagia improvement in a subset of patients with eosinophilic gastritis or duodenitis." (PMID 37138643, 2023).
glioma (1 paper, 2024). A benign or malignant brain and spinal cord tumor that arises from glial cells (astrocytes, oligodendrocytes, ependymal cells). "CLIC4 expression levels were positively correlated with specific markers of macrophages (CD80, CD86, MRC1), neutrophils (FCGR3A, FCGR3B), eosinophils (SIGLEC8, IL3RA), T cells (CD3D, CD4), CD8+ T cells (CD8A, CD8D), NK cells (NCAM1), and B cells (CD19) in glioma." (PMID 39595145, 2024).
periodontal disease (1 paper, 2021). "We also calculated the total number of identified cells (CD66b+, CD4+, CD8+, CD56+, CD68+, Siglec8+, CD138+) and OSCC patients showed significantly more cells (55,966 ± 22,151) compared to periodontal disease (32,550 ± 11,816) and control patients (6,355 ± 4,733)." (PMID 35048057, 2021).
tumor (4 papers, 2013 to 2024). "In contrast, tumor expression of SIGLEC8 was significantly higher at early pathological stages compared to stage IV; combining formerly type 1 and 2 pRCC showed similar results." (PMID 39496729, 2024).
SIGLEC8 also shares sentences with these, for which no sentence is quoted: cancer (3 papers); allergic conjunctivitis (1); allergic respiratory disease (1); Alzheimer disease (1); cholangiocarcinoma (1); eosinophilia (1); kidney chromophobe (1); melanoma (1); papillary renal cell carcinoma (1); psoriasis (1).